SDF4 (stromal cell derived factor 4)
Description:
May regulate calcium-dependent activities in the endoplasmic reticulum lumen or post-ER compartment. Isoform 5 may be involved in the exocytosis of zymogens by pancreatic acini.
Synonyms: Cab45; SDF-4
Gene: Protein-coding gene on chromosome 1 (1,216,887 to 1,238,870, reverse strand). Ensembl gene ENSG00000078808.
Subcellular location: Golgi apparatus lumen (Isoform 1); Cytoplasm (Isoform 5); Cell membrane; Cell projection, bleb
Subcellular location (Human Protein Atlas): Golgi apparatus
Genetic constraint (gnomAD): Loss-of-function variants: 19 observed, 31.87 expected, observed/expected ratio (o/e) 0.6, 90% interval 0.41 to 0.88. The upper end of that interval is the gene's LOEUF score, 0.88, which puts it in group 3 of 6, group 1 being the genes least tolerant of losing a copy. Missense variants: 440 observed, 512.91 expected, observed/expected ratio (o/e) 0.86, 90% interval 0.79 to 0.93. Synonymous variants: 235 observed, 206.07 expected, observed/expected ratio (o/e) 1.14, 90% interval 1.02 to 1.27.
Homologues: Orthologues: chimpanzee SDF4 (99% identical), guinea pig SDF4 (90% identical), mouse Sdf4 (87% identical), rat Sdf4 (87% identical), dog SDF4 (87% identical), macaque SDF4 (85% identical), pig SDF4 (84% identical), tropical clawed frog sdf4 (75% identical), zebrafish sdf4 (73% identical), Drosophila melanogaster myd (31% identical), Caenorhabditis elegans C56C10.9 (26% identical). Paralogues in human: CALU (25% identical), RCN1 (24% identical), RCN3 (24% identical), RCN2 (21% identical).
Diseases named in the same sentence as SDF4 in open-access papers:
SDF4 is named in the same sentence as 22 diseases in open-access papers, as found by Europe PMC text mining. Sharing a sentence is not in itself a finding about the gene and the disease. The quoted sentences say what the papers report.
breast cancer (3 papers, 2015 to 2021). A primary or metastatic malignant neoplasm involving the breast. "SDF4 expression was found to be significantly reduced in mammary tumours compared to normal tissue and low levels of SDF4 are linked to a poor prognosis." (PMID 31366318, 2019). "Sdf4 is a member of the stromal cell derived factor (SDFs) family and functionally classified as a chemokine; SDF-2, SDF-4 and SDF-5 are expressed in mammary tumor tissues and cells and a reduced level of SDF-2, SDF2-L1 and SDF-4 are associated with a poor clinical outcome." (PMID 26681200, 2015).
lung carcinoma (3 papers, 2021 to 2023). "We further explored the relationships between SDF4 expression and tumor angiogenesis in lung cancer specimens." (PMID 33953165, 2021). "Echoing these findings, our study showed that after chemotherapy treatment, lung cancer CAFs up­regulate SDF4 and further create a permissive environment for tumor cell angiogenesis and promotion of distant metastasis." (PMID 33953165, 2021). "Moreover, CDDP-induced CEBPD enforced the differentiation of fibroblasts toward myofibroblasts in the lung cancer microenvironment and activated the stromal cell-derived factor 4 (SDF4)/C-X-C motif chemokine receptor 4 (CXCR4) to trigger angiogenesis and distal metastasis." (PMID 36776299, 2023). "Furthermore, we examined whether anticancer drug-induced SDF4 in fibroblasts contributes to angiogenesis and metastasis of lung cancer cells." (PMID 33953165, 2021). "SDF4 interacts with CXCR4 to trigger VEGFD expression in endothelial cells and promotes the angiogenesis of lung cancer." (PMID 36606322, 2023). "Overall, high SDF4 expression was positively correlated with the endothelial cell marker CD31 and with VEGF-D signals in cisplatin-administered lung cancer patients." (PMID 33953165, 2021). "Specimens from 20 patients with lung cancer treated with cisplatin and 37 patients without cisplatin were collected to assess SDF4 abundance." (PMID 33953165, 2021). "It implies that SDF4/CXCR4 complex plays a critical and specific role in chemotherapy-regulated angiogenesis, but not SDF1/CXCR4, and consequently contribute to metastasis of lung cancer." (PMID 33953165, 2021).
pancreatic cancer (3 papers, 2014 to 2023). "While it has been shown that SDF1 is overexpressed in aggressive pancreatic tumors and high levels of SDF1 are linked to a poor prognosis, the significance of SDF4 is in pancreatic cancer is less known." (PMID 24708694, 2014). "Five proteins including CD9, perlecan (HSPG2), apolipoprotein E (APOE), stromal cell derived factor 4 (SDF4), and fibronectin receptor/integrin β1 (ITGB1) were subsequently validated by immunohistochemistry on human pancreatic cancer tissue." (PMID 24708694, 2014). "SDF4 expression was elevated in a colorectal cancer cell line and in pancreatic cancer cells compared with non-neoplastic pancreatic ductal cells." (PMID 38259614, 2023).
nasopharyngeal carcinoma (2 papers, 2023). A carcinoma arising from the nasopharyngeal epithelium. "The reversal of LINC00173-mediated cancer cell progression by SDF4 knockdown suggested the potential of the LINC00173-RAB1B-SDF4 pathway to be a drug target for nasopharyngeal cancer." (PMID 38259614, 2023). "A long non-coding RNA, LINC00173, that is upregulated in nasopharyngeal cancer cells, could promote the growth, migration and metastasis of nasopharyngeal cancer cells by interacting with RAB1B to facilitate SDF4 secretion in a RAB1B-dependent manner." (PMID 38259614, 2023).
autoimmune disease (1 paper, 2024). A disorder resulting from loss of function or tissue destruction of an organ or multiple organs, arising from humoral or cellular immune responses of the individual to their own tissue constituents. "It is located in the first intron of SDF4 and colocalizes with GWAS variants for systemic lupus erythematosus, an autoimmune disease affecting multiple organs." (PMID 38710690, 2024).
chronic kidney disease (1 paper, 2021). Impairment of the renal function secondary to chronic kidney damage persisting for three or more months. "Among all characteristics, cancer, chronic kidney disease, APACHE II score, SOFA score, and SDF4 expression levels revealed statistical significance (P < 0.1) in univariate analysis." (PMID 34326834, 2021).
endothelial dysfunction (1 paper, 2025). In vascular diseases, endothelial dysfunction is a systemic pathological state of the endothelium (the inner lining of blood vessels) and can be broadly defined as an imbalance between vasodilating and vasoconstricting substances produced by (or acting on) the endothelium. "These clinical characteristics are known to be associated with increased oxidative stress, chronic inflammation, and endothelial dysfunction, which may have contributed to the observed alterations in SDF4 levels and thiol/disulfide homeostasis." (PMID 41464845, 2025).
gastric cancer (1 paper, 2023). A primary or metastatic malignant neoplasm involving the stomach. "Considering the potential of SDF4 as a diagnostic biomarker, which is applicable for various types of malignancies other than gastric cancer, would be beneficial in large-scale population screening programs." (PMID 37730904, 2023). "In conclusion, serum SDF4 levels may be a novel diagnostic biomarker for not only advanced but also early gastric cancer." (PMID 37730904, 2023). "In addition, even if some GC cell lines produce little SDF4 in vitro, serum SDF4 levels could increase in vivo due to the heterogeneity of gastric cancer tissues or secretion from other organs." (PMID 37730904, 2023).
gastritis (1 paper, 2023). Inflammation of the stomach. "A second explanation for the lack of change in serum SDF4 levels postoperatively is that it may be produced by remnant gastric tissues, including gastric intestinal dysplastic mucosa or gastritis mucosa." (PMID 37730904, 2023).
ovarian disorder (1 paper, 2024). A disease involving the ovary. "Our findings revealed distinct cargo compositions in enhanced exosomes, featuring upregulated proteins such as EFEMP1, HtrA1, PAM, and SDF4, suggesting their potential for treating ovarian disorders." (PMID 38793064, 2024).
ovarian dysfunction (1 paper, 2024). The inability of the ovaries to function. "The overexpression of EFEMP1, HtrA1, PAM, and SDF4 in enhanced exosomes compared to naïve exosomes underscores their potential therapeutic relevance in treating ovarian dysfunction." (PMID 38793064, 2024).
Sepsis (1 paper, 2021). Sepsis is defined as life-threatening organ dysfunction caused by a dysregulated host response to infection. "Previous DNA methylation analysis revealed that the promoter region of SDF4 was hypomethylated in porcine mammary epithelial cells faced with Escherichia coli challenge, suggesting the potential effect of SDF4 in sepsis." (PMID 34326834, 2021). "To determine the role of Sdf4 in sepsis-induced lung injury, we overexpressed Sdf4 using adenovirus vector." (PMID 34326834, 2021). "In conclusion, using WGCNA analysis, our study identified SDF4 as a biomarker of sepsis prognosis, and a prediction model was established based on SDF4 expression levels and clinical characteristics." (PMID 34326834, 2021). "Upon inflammatory overload in severe sepsis, the SDF4 expression level was decreased, leading to an ER stress signaling cascade." (PMID 34326834, 2021). "We observed that SDF4 was a protective factor for sepsis patients in both the validation datasets and cohort." (PMID 34326834, 2021). "Incorporation of SDF4 can improve clinical parameters predictive value for the prognosis of sepsis, showing a potential for future applications." (PMID 34326834, 2021). "Taken together, our data indicate that ER stress may be up-regulated as a result of down-regulation of SDF4, leading to worsened sepsis outcomes." (PMID 34326834, 2021). "Finally, SDF4 was preliminarily validated using other datasets with sepsis prognosis information (GSE54514 and E-MTAB-4421)." (PMID 34326834, 2021). "SDF4 was also down-regulated in patients who would later die compared to sepsis survivors." (PMID 34326834, 2021). "Considering the decreased expression of SDF4 in sepsis patients, we investigated whether Sdf4 was down-regulated in CLP-induced sepsis in mice." (PMID 34326834, 2021). "Finally, studies elucidating dynamic changes in SDF4 and ER stress with disease process or therapeutic intervention and the molecular mechanism of SDF4 and ER stress in sepsis in vivo or in vitro might be of great significance in the future." (PMID 34326834, 2021). "Considered together, these results indicated that the Sdf4 is a negative upstream regulator of ER stress in sepsis-induced lung injury, whereas overexpression of Sdf4 attenuated excessive ER stress." (PMID 34326834, 2021).
tumor (8 papers, 2014 to 2024). "Therefore, SDF4 was selected as the final candidate for a diagnostic biomarker in this study, as a potential serum diagnostic tumor marker for GC and other cancers (breast cancer, colorectal cancer, pancreatic cancer, esophageal cancer and hepatic cancer)." (PMID 37730904, 2023). "In SDF4-positive tumor tissues, both the mucosal side and the invasive front showed positive staining." (PMID 37730904, 2023). "Moreover, we need to develop a multiplex ELISA kit that can simultaneously measure SDF4 and other serum tumor markers, thereby increasing the sensitivity and specificity for early cancer diagnosis." (PMID 37730904, 2023). "Since stage IV GC includes a variety of tumor burden and clinical features such as peritoneal dissemination, gastrointestinal stenosis, and multiple liver metastases, making it difficult to fully explain the reason for high SDF4 values in stage IV GC." (PMID 37730904, 2023). "It is speculated that elevated serum SDF4 levels may be derived from cancer cells, other cells activated under inflammatory conditions, including cells within the tumor microenvironment, or normal tissues such as the liver." (PMID 37730904, 2023). "However, it is speculated that cells in the tumor microenvironment and other inflammatory tissues might promote the production and secretion of SDF4 by tumor cells, leading to abnormally elevated serum SDF4 levels at an early stage in GC development." (PMID 37730904, 2023). "Stromal cell-derived factor 4 (SDF4) responds to anticancer drugs by activating CEBPD within CAFs, establishing a favorable environment for angiogenesis in tumor cells and facilitating distant metastasis." (PMID 39691475, 2024). "Hence, we speculated that the expression of SDF4 in CRC possessed tumor heterogeneity." (PMID 37723418, 2023). "Stromal-cell-derived factor 4 (SDF4) is responsive to anticancer drugs via CEBPD activation in CAFs and contributes to create a permissive environment for tumor cell angiogenesis and promotion of distant metastasis." (PMID 33953165, 2021). "RCN3 (r = − 0.319, p < 0.05) and CALU (r = – 0.215, p < 0.05) expressions had significantly negative correlations with tumor purity, while a weak negative correlation was observed between SDF4 expression and tumor purity (r = − 0.125, p < 0.05)." (PMID 37723418, 2023). "The role of SDF4, a calcium-binding protein that regulates calcium-dependent cellular activities, in GBM has not been described, but in other cancers, SDF4 is highly expressed and promotes tumor growth, migration, and distant metastasis." (PMID 38259614, 2023). "The SDF4 (also called CAB45) found in Ouled Jellal was involved in protecting against UV-induced damages and was revealed as a modulator of cell proliferation and tumor growth." (PMID 34925440, 2021). "One possible explanation is that SDF4 may have a very long half-life and is not eliminated from the circulation for at least 3 months after the tumor has been excised." (PMID 37730904, 2023). "SDF4 was absent from the normal tissues (the positive staining rate was 0%), but in GC tissue sections, expression was observed in the cytoplasm of cancer cells but not in the tumor stroma." (PMID 37730904, 2023). "Thus, even as the tumor progressed, there was no shift in positive staining of SDF4 to one particular tumor region, which is consistent with the lack of correlation between elevated serum SDF4 levels and cancer stage." (PMID 37730904, 2023). "Our immunohistochemical staining experiments showed that SDF4 protein is expressed in the cytoplasm of GC cells but not in the stroma or adjacent normal tissues, suggesting that serum SDF4 may indeed be derived from the GC tumor cells in vivo." (PMID 37730904, 2023).
cancer (6 papers, 2021 to 2023). A tumor composed of atypical neoplastic, often pleomorphic cells that invade other tissues. "The aim of this study was to evaluate the diagnostic significance of serum SDF4 levels in cancer patients, with a particular focus on GC." (PMID 37730904, 2023). "An elevation in SDF4 expression has been reported in several cancer cell types, particularly those with enhanced proliferative and metastatic potential." (PMID 37730904, 2023). "We demonstrated that serum SDF4 levels were significantly elevated in patients with early stage GC compared with healthy subjects, as well as in patients with cancers representing different histological types than adenocarcinoma." (PMID 37730904, 2023). "Here, we conducted a single-institutional study to evaluate the diagnostic performance of serum stromal cell-derived factor 4 (SDF4) levels in cancer patients." (PMID 37730904, 2023). "The median serum SDF4 level for the 80 healthy controls was 83.8 pg/ml (range, 17.9–169.9 pg/ml) and higher values were obtained for all cancer patient groups." (PMID 37730904, 2023). "Taken together, our novel findings support that SDF4 can be a therapeutic target in inhibition of angiogenesis for chemotherapy drug-administrated cancer patients." (PMID 33953165, 2021). "Serum SDF4 levels were higher in patients with cancer than the healthy control in all cancer type." (PMID 37730904, 2023). "Finally, our results demonstrated the potential diagnostic utility of serum SDF4 levels but did not identify the cell/tissue origin or biological functions of SDF4 in cancer patients." (PMID 37730904, 2023). "Furthermore, and importantly, we demonstrated the clinical significance of this finding by showing that there is a significant induction of SDF4 in the stroma of CDDP-treated human cancer tissues." (PMID 33953165, 2021). "However, the detailed regulation of SDF4 and the SDF4-mediated effects on tumorigenesis, including its potent link with the metastatic potential of cancer cells and angiogenesis, remain an open question." (PMID 33953165, 2021). "SDF4 was suggested to be regulated in Ca2+-dependent secretory cargo sorting pathways in the trans-Golgi network (TGN), exhibited increased expression in multiple types of cancer cells with higher proliferation and metastatic potential and was shown to promote cancer cell migration." (PMID 33953165, 2021).
SDF4 also shares sentences with these, for which no sentence is quoted: adenocarcinoma (2 papers); cervical cancer (1); colorectal cancer (1); coronary heart disease (1); glioma (1); melanoma (1); rheumatoid arthritis (1); systemic lupus erythematosus (1).